INPP1 (inositol polyphosphate-1-phosphatase)
Description:
Mg(2+)-dependent phosphatase that catalyzes the hydrolysis of the 1-position phosphate from inositol 1,4-bisphosphate and inositol 1,3,4-trisphosphate and participates in inositol phosphate metabolism.
Tractability: PROTAC: ubiquitination databases record sites on it; its protein half-life has been measured.
Gene: Protein-coding gene on chromosome 2 (190,340,590 to 190,371,665, forward strand). Ensembl gene ENSG00000151689.
Subcellular location (Human Protein Atlas): Centriolar satellite; Cytosol
Pathways (Reactome):
Metabolism: Synthesis of IP2, IP, and Ins in the cytosol
Gene Ontology:
Molecular function: protein binding; inositol-1,3,4-trisphosphate 1-phosphatase activity; inositol-1,4-bisphosphate 1-phosphatase activity
Biological process: phosphate-containing compound metabolic process; signal transduction; phosphatidylinositol phosphate biosynthetic process
Cellular component: cytosol
Genetic constraint (gnomAD): Loss-of-function variants: 3 observed, 9.54 expected, observed/expected ratio (o/e) 0.31, 90% interval 0.14 to 0.81. That is too few expected variants to judge how well the gene tolerates losing a copy. Missense variants: 337 observed, 383.55 expected, observed/expected ratio (o/e) 0.88, 90% interval 0.8 to 0.96. Synonymous variants: 125 observed, 145.26 expected, observed/expected ratio (o/e) 0.86, 90% interval 0.74 to 1.
Homologues: Orthologues: chimpanzee INPP1 (99% identical), pig INPP1 (85% identical), rabbit INPP1 (84% identical), guinea pig INPP1 (83% identical), mouse Inpp1 (81% identical), rat Inpp1 (80% identical), macaque INPP1 (79% identical), dog INPP1 (77% identical), zebrafish si:ch211-160o17.2 (44% identical), Drosophila melanogaster Ipp (38% identical). Paralogues in human: BPNT1 (22% identical), BPNT2 (21% identical), IMPA2 (16% identical), IMPA1 (15% identical).
Diseases named in the same sentence as INPP1 in open-access papers:
INPP1 is named in the same sentence as 12 diseases in open-access papers, as found by Europe PMC text mining. Sharing a sentence is not in itself a finding about the gene and the disease. The quoted sentences say what the papers report.
autism (1 paper, 2014). Persistent deficits in social interaction and communication and interaction as well as a markedly restricted repertoire of activity and interest as well as repetitive patterns of behavior. "Single nucleotide polymorphisms in PIK3CG, TSC1/2, which is mutated in the autism spectrum disorder tuberous sclerosis (TS), and INPP1, inositol polyphosphate-1-phosphatase, were shown to be in linkage disequilibrium in patients with autism." (PMID 24592210, 2014).
bipolar disorder (1 paper, 2011). A disorder of the brain that causes unusual shifts in mood, energy, activity levels and the ability to carry out day-to-day tasks. "Reduced inositol-dependent signalling was the first proposed mechanism for bipolar disorder treatments, primarily based on a lithium-induced attenuation of inositol recycling through inhibition of inositol monophophatase (IMPase) and inositol polyphosphate 1-phosphatase (IPPase)." (PMID 21093602, 2011).
cervical cancer (1 paper, 2021). A primary or metastatic malignant neoplasm involving the cervix. "Another similar study on miR-27a also showed that miR-27a was highly expressed in cervical cancer tissues, promoted the expression of the target gene inositol polyphosphate-1-phosphatase (INPP1), and promoted tumorigenic activity." (PMID 33967611, 2021).
colorectal cancer (1 paper, 2015). A primary or metastatic malignant neoplasm that affects the colon or rectum. "A deregulated activity of INPP1 has also been demonstrated in colorectal cancer and in prostate cancer, where it has been proposed as therapeutic target." (PMID 26359356, 2015). "The over expression in colorectal cancer of INPP1 was primary described by Bustin and colleagues." (PMID 26359356, 2015).
cancer (7 papers, 2015 to 2024). A tumor composed of atypical neoplastic, often pleomorphic cells that invade other tissues. "Evidences show that inactivation of INPP1 leads to a reduction in glycolytic intermediates; this reduction impairs cancer cell motility, invasiveness, and tumorigenicity via a complex feed-forward mechanism." (PMID 27708222, 2016). "The research reported that inositol polyphosphate phosphatase 1 (INPP1), as a key enzyme in inositol phosphate metabolism, could drive cancer aggressiveness by reducing glycolysis and lipid metabolism, which was consistent with the results of our study." (PMID 39450338, 2024). "INPP1 is highly expressed in aggressive human cancer cells and primary high-grade human tumors." (PMID 34585118, 2021). "In one report, LPA was found to induce glycolysis in microglial cells, and in another, inositol polyphosphate phosphatase 1 (INPP1), which is highly expressed in various aggressive cancer cells, was found to promote glycolysis and stimulate LPA synthase in a feed-forward mechanism." (PMID 30384405, 2018). "Although Inpp1 has not been widely investigated in the context of gastrointestinal cancers, it has been shown to be involved in regulation of cancer cell activity via lipid lysophosphatidic acid signaling and thereby, impact cell migration and growth." (PMID 38730628, 2024).
tumor (1 paper, 2022). "We found that all tumor cells share the vast majority of these mutations (i.e., they are clonal), including variants affecting genes previously associated with CRC progression (e.g., INPP1, CDC5L, ROR2, EXOSC5)." (PMID 35081992, 2022).
INPP1 also shares sentences with these, for which no sentence is quoted: autism spectrum disorder (1 paper); breast carcinoma (1); HTLV infection (1); male infertility (1); prostate carcinoma (1); tuberous sclerosis (1).